ARID1A (AT-rich interaction domain 1A)
Diseases named in the same sentence as ARID1A in open-access papers (continued):
Sharing a sentence is not in itself a finding about the gene and the disease.
gastric cancer (continued). "Interestingly, loss of ARID1A is closely associated with MSI and EBV, which can lead to immune infiltration, activate the immune system to kill tumor cells, and appear to be a favorable prognostic factor in gastric cancer." (PMID 37366273, 2023). "The role of multiple PARP inhibitors has also been evaluated in gastric cancer (GC) conditions as mutated homologous DNA recombination genes such as BRC1/2, PALB2, ATM, RAD51C, and ARID1A carry somatic HRD." (PMID 35873570, 2022). "Interestingly, the phosphorylation sites identified (Ser1316/Ser1320) also lie in the conserved β-TrCP degradation motif (DSGXXS degron), and β-TRCP, an E3 ligase that preferentially binds to phosphorylated substrates, is known to degrade ARID1A in gastric cancer cells." (PMID 36435834, 2022). "Similarly, gastric cancer samples exhibit absents or weak ARID1A protein expression even though there were no detectable ARID1A mutations." (PMID 34414106, 2021). "Moreover, an experimental study conducted on gastric cancer cells, infected with a CagA H. pylori strain revealed an increase in miRNA-223 expression through NF-κB signaling and also a downregulation of ARID1A (AT-rich interacting domain containing protein 1A), an inhibitor of carcinogenesis." (PMID 33573346, 2021). "Next, we investigated whether ARID1A expression has prognostic value in early-stage gastric cancer." (PMID 31043675, 2019). "Therefore, evaluation of ARID1A expression in gastric cancer will increase our understanding of impaired MMR and tumor phenotypes, and may lead to development of novel immune checkpoint blockade therapies." (PMID 31043675, 2019). "Therefore, our findings suggest that NF-κB/miR-223-3p/ARID1A axis may link the process of H. pylori-induced chronic inflammation to gastric cancer and miR-223-3p may serve as a novel target for the intervention of the malignance." (PMID 29317648, 2018). "Furthermore, the overexpression of ARID1A deprived the miR-223-3p-mediated promotion of gastric cancer cell proliferation and migration, suggesting that the miR-223-3p played the oncogenic role in gastric cancer by directly targeting ARID1A." (PMID 29317648, 2018). "In addition, we detected lower ARID1A immunoreactivity in poorly differentiated gastric cancer tissues than in well-differentiated ones, suggesting that decreased ARID1A expression might play a role in tumor de-differentiation." (PMID 22808142, 2012). "Notably, ARID1A expression appears to play a crucial role in modulating the tumor microenvironment and influencing the response to immunotherapy in gastric cancer (GC)." (PMID 38893181, 2024). "In gastric cancer and hepatocellular carcinoma, the E3 ubiquitin ligase complex SCF promotes degradation of ARID1A, which is triggered by ATM activation due to DNA damage in gastric cancer and by mTORC1 activation in hepatocellular carcinoma." (PMID 39048965, 2024).
gastric cancer (continued). "Therefore, ARID1A might interact with ICIs in the treatment of stomach cancer." (PMID 36276268, 2022). "This analysis indicated that short periods of M4344 treatment were sufficient to elicit antitumor gastric cancer PDX responses, especially in PDX with either ARID1A or ATM defects." (PMID 36273494, 2022). "ARID1A affects the process of EMT in multiple cancers, such as gastric cancer, neuroblastoma, and liver cancer." (PMID 34671561, 2021). "Especially with regard to a possible determination of SWI/SNF status in routine diagnostics, it seems reasonable to limit the determination of SWI/SNF status in gastric cancer to SMARCA4, SMARCA2, and ARID1A." (PMID 34359794, 2021). "We provide a novel molecular mechanism for the negative regulation of ARID1A by β-TRCP and ATM in gastric cancer cells in response to DNA damage insult." (PMID 31210753, 2019). "Our studies provide a novel molecular mechanism for the negative regulation of ARID1A by β-TRCP and ATM in DNA damaged gastric cancer cells." (PMID 31210753, 2019). "In contrast, there are only 6 gastric cancer samples showing absent or weak protein expression in the absence of detectable ARID1A mutation, which suggests that other mechanisms may contribute to ARID1A inactivation." (PMID 22808142, 2012). "ARID1A, a member of the SWI/SNF chromatin remodeling complex, has gained increasing attention in cancer research due to its roles in tumor initiation and suppression in several tumor types other than gastric cancer." (PMID 38893181, 2024). "Additionally, alterations in ARID1A interact with the PI3K/Akt/mTor pathway in nasopharyngeal carcinoma and gastric cancer cell lines." (PMID 38600891, 2024). "Investigations have unveiled the pivotal role of ARID1A in bridging the gap between genome instability and the reconfiguration of the tumour immune microenvironment, culminating in an enhanced response to ICI within the landscape of gastric cancer treatment." (PMID 38041544, 2023). "Since gastric cancer with the MSI-H subtype and PD-L1 positive expression more effectively responds to immune checkpoint inhibitors (ICIs), the expression of ARID1A may become a biomarker for GC immunotherapy." (PMID 38008753, 2023). "Further hierarchical analysis found that PD‐L1 was highly expressed in gastric carcinomas with high CD8+ T infiltration only when ARID1A was negative." (PMID 37366273, 2023). "The analyses of the GEO database showed the decreased Arid1a mRNA expression in hepatitis C patients (GSE38597), gastric cancer infected with Epstein Barr virus, epithelial cell model of kaposarcoma virus infection (GSE1377), and cervical cancer infected with human papillomavirus." (PMID 34315861, 2021). "Knockdown of ARID1A decreased HRK expression without direct binding to the HRK gene in gastric cancer cells." (PMID 34799565, 2021). "It was known that mutations in genes such as CDH1, PIK3CA, ARID1A (AT-rich interactive domain 1A), EGFR, and PTEN existed in gastric cancer, providing potential circulating DNA for detection of gastric cancer." (PMID 33693004, 2021). "Second, the panel used in the present study lacked several genes that are frequently mutated in gastric cancer such as RHOA and ARID1A." (PMID 33027286, 2020). "EBV-positive gastric cancer was frequently identified in ARID1A-negative cases (4 of 16 cases, 25%) compare to ARID1A-positive cases (0 of 21 cases, 0%) (P = 0.028)." (PMID 31043675, 2019). "In the combined cohorts, ARID1A had no prognostic value in stage 1, stage 2, or stage 1&2 gastric cancer." (PMID 31043675, 2019). "PD-L1 was significantly overexpressed in ARID1A-negative gastric cancer in our combined cohorts (P = 0.0007)." (PMID 31043675, 2019).
gastric cancer (continued). "Consistent with previous reports, we showed that PD-L1 is overexpressed in gastric cancer lacking ARID1A expression." (PMID 31043675, 2019). "An ARID1A-knockdown gastric cancer cell line was subjected to microarray analysis, but no actionable targets or pathways were identified." (PMID 31043675, 2019). "In the clinical setting, the level of miR-223-3p is upregulated, while ARID1A is downregulated significantly in human gastric cancer tissues compared with the corresponding noncancerous tissues." (PMID 29317648, 2018). "Furthermore, the expression of ARID2 and its family members is lost during gastric cancer progression, but the effect of ARID2 on tumor progression is weaker than that of ARID1A." (PMID 27270314, 2016). "Results revealed decreased ARID1A mRNA (P = 0.0029) and protein (P = 0.0015) expression in most tumor-bearing tissues compared with the matched adjacent non-tumor tissues, and in gastric cancer cell lines." (PMID 22808142, 2012). "In the current study, we demonstrated that ARID1A was expressed at both lower mRNA and protein level in gastric cancer tissues than corresponding non-cancerous mucosa." (PMID 22808142, 2012). "Therefore, the relationship between ARID1A alterations and MSI status in gastric cancer, as well as its clinicopathological significance, needs further investigation in the future research." (PMID 22808142, 2012). "AT-rich interaction domain 1A (ARIDA), which encodes the BAF250a subunit of the Switch/Sucrose Non-Fermentable (SWI/SNF) chromatin remodeling complex, is recurrently mutated across cancers, including ovarian clear cell, endometrial, and gastric carcinomas." (PMID 41215803, 2025). "This indicates that miR‐7641 directly regulates ARID1A in a negative way in gastric cancer." (PMID 38041544, 2023). "Notably, the loss of ARID1A protein expression is associated with the absence of MMR proteins and MSI in gastric carcinoma." (PMID 38041544, 2023). "Moreover, a negative correlation between miR-223-3p and ARID1A expression is found in the gastric cancer tissues." (PMID 29317648, 2018). "We also determined the expression of ARID1A in the paired gastric cancer and corresponding noncancerous tissues and found that 28/42 (66.7%) of the gastric cancer specimens showed significantly decreased expression of ARID1A as compared with corresponding noncancerous tissues." (PMID 29317648, 2018). "However, thus far the expression, clinical significance and biological functions of ARID1A in gastric cancer have not been explored." (PMID 22808142, 2012). "Here, in a larger gastric cancer population (224 cases), we found that the loss of ARID1A expression was significantly correlated with a higher T stage of gastric cancer, implying that absence of ARID1A expression may promote tumor growth and invasion." (PMID 22808142, 2012). "Hence, gastric cancer lacking ARID1A expression may be more sensitive to PD-1-PD-L1 immune checkpoint therapies." (PMID 36890819, 2023). "Therefore, we confirmed that the cohorts used in the present study were suitable for analysis, and that gastric cancer lacking ARID1A expression may be sensitive to PD-1-PD-L1 immune checkpoint therapies." (PMID 31043675, 2019). "Unlike ARID1A, the increased expression of BRG1, the ATPase subunit of the SWI/SNF complex, appeared to correlate with gastric cancer development and metastasis." (PMID 36653445, 2023). "However, the relationship between ARID1A and CD47 expression and their prognostic value in gastric cancer (GC) are still unknown." (PMID 34805154, 2021).
endometrial cancer (140 papers, 2012 to 2026). Primary or metastatic malignant neoplasm involving the endometrium (mucous membrane that lines the endometrial cavity). "Autocrine activation of JAK/STAT3 signal by OSM in ARID1A-deficient endometrial cancer cells promotes PLK1 levels, inducing mitotic abnormality." (PMID 41800254, 2026). "Our study indicates that OSM-STAT3-PLK1 axis inhibition presents a new therapeutic approach for endometrial cancer with ARID1A loss." (PMID 41800254, 2026). "In some endometrial cancers, ARID1A loss has been linked to the activation of oncogenic pathways, such as the PI3K/AKT/mTOR signaling pathway." (PMID 40072110, 2025). "In certain high-grade endometrial cancers, mutations in ARID1A, a chromatin remodeling gene, and RAS pathway genes frequently co-occur with PIK3CA mutations." (PMID 40072110, 2025). "In endometrial cancer, ARID1A mutations result in epigenetic alterations that drive oncogenesis by disrupting normal cell growth, differentiation, and DNA repair mechanisms." (PMID 40072110, 2025). "This can lead to the clinical investigation of EZH2 inhibitors, such as tazemetostat, which have been evaluated in basket trials that included cohorts of endometrial cancer patients with ARID1A-mutated tumors." (PMID 40940815, 2025). "ARID1A mutations are particularly prevalent in gynecologic cancers (detected in 10%–60% of ovarian and endometrial carcinoma cases), especially in premalignant gynecological lesions of endometrioid origin." (PMID 39932052, 2025). "Mutations in ARID1A are more commonly associated with endometrioid and clear cell subtypes of endometrial carcinoma, with mutation rates reported between 40 and 50% in endometrioid tumors and 30–50% in clear cell carcinomas." (PMID 40072110, 2025). "In a study of 50 endometrial carcinomas evaluating the correlation of ARID1A mutations with RNA and protein expression, 22/50 samples were lacking ARID1A expression." (PMID 40429787, 2025). "In summary, this work underscores the importance of incorporating genetic profiling (e.g. ARID1A/B mutational status) in the evaluation of endometrial carcinomas and during DDEC classification." (PMID 41279405, 2025). "In ARID1A-deficient endometrial cancer cells, the level of FOXO1 increased while the mitogen-activated protein kinase pathway (MAPK) and insulin-like growth factor-1 signaling pathway decreased." (PMID 38893147, 2024). "In endometrial cancer cells with Arid1a mutations, increased susceptibility to PARP inhibitors is observed, due to the NHEJ-repair defects caused by the Arid1a mutation." (PMID 39123453, 2024). "In endometrial cancers, especially in clear cell and endometrioid subtypes, mutations of ARID1A (AT-rich interaction domain 1A gene), which codes a subunit of the SWI/SNF chromatin remodeling complex, are very frequent." (PMID 38893147, 2024). "The identification of these variants contributes to the growing body of evidence that ARID1A loss is a critical event in the development of endometrial cancer, particularly in its more aggressive forms." (PMID 39296440, 2024). "If ARID1A mutations are detected through genetic testing in patients with endometrial cancer in clinical practice, ICIs should be considered the recommended treatment, based on previous reports." (PMID 38893118, 2024). "ARID1A mutations are frequently detected in patients with endometrial cancer, and cell line assays have indicated increased tumorigenicity when ARID1A mutations are combined with other genomic abnormalities." (PMID 36797358, 2023). "Approximately 6% of human cancers have ARID1A mutations that cause its inactivation, and these mutations are seen most frequently in clear cell ovarian cancers (~ 50%), endometrial cancers (~ 37%), gastric cancers (20–30%), and bladder cancers (~ 20%) s)." (PMID 38071325, 2023). "Recent circulating tumor DNA data suggest that endometrial cancer is the tumor localization with the highest ARID1A mutation rate (21%)." (PMID 37353806, 2023).
endometrial cancer (continued). "Typically, ARID1A loss is indicative of endometrioid-origin cancers; ARID1A mutations are found in 40% of endometrial cancers, 32% of endometrioid OCs, 29% of clear-cell OCs, and only 3% of HGSOC cases." (PMID 36982928, 2023). "Like endometrial carcinoma, ARID1A loss occurs most commonly in the MSI (37.9%) and NSMP (16.5%) groups, and has a synergistic effect with mutations of the PI3K/PTEN axis." (PMID 38275587, 2023). "Conversely, a separate study showed loss of ARID1A, mutated in endometrial carcinoma, preferentially affects SEs over TEs." (PMID 37415185, 2023). "ARID1A is likely to be pathogenic rather than a ‘passenger’ mutation in these MSI endometrial cancers, as ARID1A loss was found in only 14% of Lynch syndrome MSI endometrial carcinomas compared to 75% of sporadic MSI endometrial carcinomas in one study." (PMID 38275587, 2023). "In a subset of microsatellite stable (MSS) endometrial cancer cases, ARID1A’s loss has been associated with a better prognosis and indicated as a potential prognostic biomarker." (PMID 36430148, 2022). "In ovarian and endometrial cancers, ARID1A mutations often co-occur with PI3K/AKT pathway gene KRAS, PIK3CA, and PTEN alterations." (PMID 36430148, 2022). "Here, we show that deficient expression of ARID1A confers increased aggressiveness and metastatic capacity to endometrial cancer cells, while increasing HDAC6 levels." (PMID 35167193, 2022). "Studies conducted in both OCCC and in endometrial carcinoma have shown that ARID1A mutations are found in 50 and 30% of patients, respectively and that patients with tumors carrying ARID1A mutations have worse prognosis as compared with patients who do not." (PMID 36082022, 2022). "Mutations in ARID1A are frequent across carcinomatous types, present in over 30–50% of ovarian and endometrial carcinomas, 10% of hepatocellular and urinary bladder carcinomas, and 5–10% of colorectal, gastric, and non-small cell lung carcinomas." (PMID 35125107, 2022). "AT‐rich interactive domain‐containing protein 1A (ARID1A) loss‐of‐function mutation accompanied by a loss of ARID1A protein expression is frequently observed in endometrial carcinomas." (PMID 35167193, 2022). "The prognostic impact of ARID1A loss in cohorts of patients with endometrial cancer of various histological types and/or stages was rarely observed." (PMID 34257552, 2021). "Currently, one large-scale sequencing study has focused specifically on endometrial cancer metastasis, and frequent, subclonal ARID1A mutations were observed in metastatic lesions." (PMID 34941867, 2021). "Molecular alterations accompanied with ARID1A loss in each stage of endometrial cancer should be elucidated in future investigations to clarify the role of ARID1A in endometrial carcinogenesis and tumor progression." (PMID 34257552, 2021). "Loss of ARID1A expression has been associated with sporadic MSI in endometrial carcinoma secondary to MLH1 gene promoter methylation." (PMID 33608032, 2021). "In endometrial cancers, ARID1A has been reported as a causative gene of microsatellite instability by having a role in epigenetic silencing of the MLH1 gene." (PMID 31731647, 2019).